HCCS (holocytochrome c synthase)
Diseases named in the same sentence as HCCS in open-access papers (continued):
Sharing a sentence is not in itself a finding about the gene and the disease.
tumor (4 papers, 2020 to 2026). "Recent studies suggest that altered expression of mitochondrial genes, including HCCS, may be associated with tumor aggressiveness and therapy resistance." (PMID 41476662, 2025). "Notably, HCCS expression was significantly higher in patients with advanced nodal metastasis and later tumor stages, indicating a possible association with disease progression." (PMID 41476662, 2025). "Additionally, we identified a network of genes co‐expressed with HCCS, both positively and negatively, suggesting that HCCS might engage in complex molecular pathways associated with tumor growth and metastasis." (PMID 41476662, 2025). "In vitro validation confirmed that HCCS is a key driver of tumor growth, as HCCS knockdown significantly inhibited cell proliferation and colony-forming ability by inducing G0/G1 phase arrest." (PMID 42232519, 2026). "The simultaneous enrichment of Tregs further supports the idea that HCCS overexpression contributes to immune evasion and tumor progression." (PMID 41476662, 2025). "Although direct tumor grade data were not analyzed, HCCS upregulation in TNBC and metastatic cases—both often correlated with higher tumor grade—implies a possible link between HCCS expression and tumor aggressiveness." (PMID 41476662, 2025). "To strengthen these observations, we examined HCCS expression at both the mRNA and protein levels in tumor tissues." (PMID 41476662, 2025). "The transcriptomic analysis supported high expression levels of HCCS across several tumor types, consistent with proteomic data." (PMID 41476662, 2025). "Our results revealed a set of genes positively correlated with HCCS expression, suggesting that HCCS may play a role in cooperative signaling pathways that promote tumor growth, mitotic stability, and metastasis." (PMID 41476662, 2025). "Importantly, HCCS expression did not significantly differ between tumor and normal tissues, reinforcing the notion that its dysregulation is not universal across malignancies." (PMID 41476662, 2025).
mitochondrial disease (1 paper, 2024). "Although not directly related to early ocular GRNs, mitochondrial disease caused by variants in HCCS, COX7B, and NDUFB11 has also been previously associated with MAC cases." (PMID 38821055, 2024).
neurodegenerative disease (1 paper, 2016). A disorder of the central nervous system characterized by gradual and progressive loss of neural tissue and neurologic function. "We find that a neurodegenerative disease-associated hCCS mutation abrogates the interaction with SOD1 by inhibiting hCCS zinc binding." (PMID 27282955, 2016). "Here we have shown reduced metalation resulting from the R163W neurodegenerative disease-associated mutation in hCCS; a situation analogous to the diminished zinc affinity of ALS-SOD1 mutants." (PMID 27282955, 2016).
HCCS also shares sentences with these, for which no sentence is quoted: congenital cataracts (1 paper); congenital glaucoma (1); developmental delay (1); glaucoma (1); head and neck squamous cell carcinoma (1); Hearing impairment (1); infection (1); invasive lobular carcinoma (1); linear skin defects with multiple congenital anomalies (1); linear skin defects with multiple congenital anomalies 1 (1); lung adenocarcinoma (1); lung squamous cell carcinoma (1); medullary carcinoma (1); microcephaly (1); paraganglioma (1); pheochromocytoma (1); septal defect (1); Thrombocytopenia (1); thyroid carcinoma (1); uterine corpus endometrial carcinoma (1); X-link disease (1).